AQP1 (aquaporin 1 (Colton blood group))
Diseases named in the same sentence as AQP1 in open-access papers (continued):
Sharing a sentence is not in itself a finding about the gene and the disease.
melanoma (continued). "Using targeted silencing of AQP1 gene expression, an impairment in the organization of F-actin and a reduced migration capacity was demonstrated in human endothelial and melanoma cell lines." (PMID 19584911, 2009). "Firstly, AQP1 plays the same role in human melanoma and endothelial cells, suggesting that this water channel has a global physiological role." (PMID 19584911, 2009). "The incidence of lung metastases was also increased, and the osmotic water permeability of the plasma membrane was increased by a factor of 5–10 in B16F10 melanoma cells and 4 T1 mammary gland tumour cells after intravenous infusion of tumour cells exhibiting AQP1 expression." (PMID 38336645, 2024). "Similar findings were also noted in AQP1-silenced human melanoma cells." (PMID 37762642, 2023). "The NC clusters Hapln1 and Aqp1 expressed melanoma dissemination and NC cell migration genes." (PMID 37605008, 2023). "Together with the survival analysis performed in this study, our results suggest that the expression of AQP1, -8, and -9 could be correlated with a better prognosis for malignant melanoma." (PMID 38002749, 2023). "In wild-type and AQP1-null model mice, both of which were implanted with melanoma cells, there were remarkably impaired tumor growth in AQP1-null mice, after subcutaneous or intracranial tumor cell implantation, which were accompanied by reduced tumor vascularity and extensive necrosis." (PMID 35847914, 2022). "Aggressive melanomas were shown to have higher expression of AQP1." (PMID 30934923, 2019). "Silencing of AQP1 using siRNA in HMEC-1 human endothelial cells resulted in a lack of F-actin polarisation at the leading edge of the plasma membrane and failure of these cells to organise a cord-like network in vitro, the finding also demonstrated in AQP1-silenced WM115 human melanoma cells." (PMID 28146084, 2017). "Blockade of AQP1 may play a role in reducing VM in vivo due to the hypoxic tumour microenvironment, as was previously reported in a melanoma xenograft model." (PMID 29104239, 2017). "Thus, AQP1 accelerates migration of endothelial, epithelial and melanoma cells, suggesting a role in vasculogenesis and cancer spread." (PMID 25719758, 2015). "Similarly, targeted disruption of AQP1 expression decreased cell motility in a malignant melanoma model." (PMID 25821338, 2015). "Interestingly, in AQP-1 null mice cell migration of melanoma cells was greatly impaired with abnormal in vitro vessel formation." (PMID 19584911, 2009). "Finally, in order to assess if their effects were restricted to a specific melanoma cell line or AQP1 plays a global physiological role, we also analyzed a human endothelial cell line." (PMID 19584911, 2009). "In fact, AQP1 has been reported to interact with focal adhesion kinases, promoting cell migration in chick neural crest cells and bone marrow mesenchymal stem cells, and to modulate actin cytoskeleton reorganization by interacting with Lin-7/β-catenin in human endothelial and melanoma cells." (PMID 39941100, 2025). "In this retrospective observational study, we evaluated the correlation between AQP1, -8, and -9 expression and the clinical outcomes of 58 patients diagnosed with MM from 2014 to 2016, of which 14 were diagnosed as nodular melanoma (NM) and 44 as superficial spreading melanoma (SSM)." (PMID 38002749, 2023). "A study showed that AQP1 silencing by siRNA in HMEC-1 human endothelium cells and WM115 human melanoma cells led to a scarcity of F-actin polarization at the plasma membrane and an inability to form a cord-like cluster in vitro.." (PMID 38336645, 2024). "Because treatment of AQP1-silenced WM115 human melanoma cells with the proteasome inhibitor MG132 induced the recovery of β-catenin, it has been suggested that AQP1 negates proteasomal degradation of β-catenin to augment Wnt signalling pathway." (PMID 28146084, 2017).
melanoma (continued). "Stimulation of migration by AQP1 was already described in a large number of cells, including proximal tubular cells, aortic endothelial cells, CHO cells and human melanoma cells." (PMID 25719758, 2015). "The expression of AQP3, as well as AQP1, AQP5, and AQP9 seem to be correlated with melanoma progression, indicating a common pattern of downregulation from the higher values in normal skin and benign nevi." (PMID 20805891, 2010). "Three proteins of this family (AQP1, AQP3, and AQP9) have probes that seem correlated with melanoma progression, all losing their expression in the process of going from normal skin to metastatic melanoma." (PMID 20805891, 2010). "Herein, we show, for the first time, in two different cell line expressing AQP1, a human melanoma cell line WM115 and a human microvascular cell line HMEC-1 that the knock down of AQP1 induced a re-organization of F-actin and affected the cell shape." (PMID 19584911, 2009). "Saadoun and colleagues found that mice lacking AQP1 and implanted with melanoma cells showed a reduced density of tumor microvessels, slower tumor growth, and increased survival." (PMID 37762642, 2023). "When the predictive power of all of these genes was tested on an ICI-treated melanoma patient cohort, 11 out of the 13 in vitro stable (containing IRGs SOX4, DEK, and HSPA1B) and AQP1 and CDCA4 in vivo stable DEGs were differentially expressed in the tumors of ICI responder melanoma patients." (PMID 35269844, 2022). "AQP1 was found to be overexpressed in BRAF-mutant melanoma tumors and was shown to be a negative prognostic factor." (PMID 35269844, 2022). "Lin-7, another component of cadherin-catenin complex which interacts with PDZ domain of β-catenin, was shown to co-immunoprecipitate with AQP1 in WM115 human melanoma and HMEC-1 human endothelial cells and its protein expression was reduced by siRNA down-regulation of AQP1." (PMID 28146084, 2017). "Silencing of AQP1 using siRNA in WM115 human melanoma and HMEC-1 human endothelial cells resulted in a lack of polarisation of F-actin at the leading edge of plasma membrane and failure of these cells to organise a cord-like network in vitro." (PMID 28146084, 2017).
Hydrocephalus (30 papers, 2010 to 2025). Hydrocephalus is an active distension of the ventricular system of the brain resulting from inadequate passage of CSF from its point of production within the cerebral ventricles to its point of absorption into the systemic circulation. "In kaolin-induced hydrocephalus mouse models, AQP1-deficient mice exhibited a reduction in ventricular size compared to wild-type mice." (PMID 39908266, 2025). "The changes in AQP1 localisation were associated with other ultrastructural changes reported by other authors in relation to the choroid plexus in hydrocephalus." (PMID 20860832, 2010). "AQP1, which is located on the choroid plexus epithelium and plays a role in CSF production, has been implicated in the development of hydrocephalus using the kaolin-induced hydrocephalus model in mice." (PMID 39364470, 2024). "Reduced AQP1 expression on the CP's surface may account for how water molecules pass through the membrane of transmembrane CP cells and into the ventricle where they create CSF and cause hydrocephalus." (PMID 36204139, 2022). "Differential changes in AQP1 expression may be associated with different types of hydrocephalus." (PMID 35715859, 2022). "All these findings support a role for AQP1 in facilitating CP secretion of CSF into the cerebral ventricles, and support the hypothesis of a role for AQP1 inhibitors in treating hydrocephalus and benign intracranial hypertension, which are associated with CFS formation or accumulation." (PMID 21119881, 2010). "AQP4 and AQP1 are among the most extensively studied aquaporins, with AQP4 promoting CSF absorption during hydrocephalus events, and AQP1 serving as the basis for CSF secretion." (PMID 39908266, 2025). "AQP1 is expressed on the apical membrane of the choroid plexus and can leak into the CSF in cases of obstructive hydrocephalus in term-pregnancy infants, serving as a potential diagnostic biomarker." (PMID 39908266, 2025). "Aquaporins (AQPs), especially AQP1 and AQP4, play a fundamental role in CSF dynamics and have been implicated in the pathophysiology of hydrocephalus." (PMID 40722587, 2025). "AQP1 and AQP4 play a role in CSF production and water removal from the brain and, thus, have been implicated in the development of hydrocephalus." (PMID 39364470, 2024). "Mice with kaolin-induced hydrocephalus demonstrated a 50% reduction of AQP1 by endocytic retrieval and reduced ventricular size of the AQP-1 null mice." (PMID 39364470, 2024). "The quick decline in AQP1 expression during the early stages of hydrocephalus is consistent with a decrease in CSF compensatory production, corroborating our theory." (PMID 36204139, 2022). "AQP1, through its polar distribution, mainly plays a role in promoting CSF production, maintaining the balance of hydrocephalus, and participating in pathological processes." (PMID 36204139, 2022). "These factors justify further investigation of AQP1 as a potential novel target for the treatment of hydrocephalus." (PMID 36204139, 2022). "Although the CSF production in mice with knockout AQP1 was reduced by only thirty percent, this was sufficient to affect the formation of hydrocephalus, suggesting that inhibition of AQP1 is a possible target." (PMID 35715859, 2022). "Three of the most well recognized and studied proteins implicated in hydrocephalus are NKCC1, Aquaporin-1 (AQP-1), and Aquaporin-4 (AQP-4)." (PMID 35306341, 2022). "Existing experimental research has demonstrated a strong correlation between the development of hydrocephalus and the overexpression of AQP1." (PMID 36204139, 2022). "Some studies have shown decreased, unchanged, and increased activity of AQP1 in different forms of hydrocephalus." (PMID 34952604, 2021). "In fact, some antagonists of both AQP1 and AQP4 are already under investigation for their translational value in conditions in which these channels are implicated—like hydrocephalus." (PMID 30967147, 2019).
Hydrocephalus (continued). "The proposed adaptive and protective roles of AQP1 and-4 as regulators of CSF production and absorption in the pathophysiology of hydrocephalus, establishes these AQPs as interesting candidates for possible treatment options." (PMID 27357498, 2016). "In mice, it has been shown that AQP1 is down-regulated after induction of hydrocephalus, rather suggesting a compensatory response to hydrocephalus, however, another study showed unchanged AQP1 expression in a rat model of hydrocephalus." (PMID 27357498, 2016). "A recent literature search for articles on the role of AQP1 in hydrocephalus found just 5 papers, 3 on animal models and 2 on humans." (PMID 25165051, 2014). "While there are some studies of AQP1 in experimental hydrocephalus, there is a paucity of human data in relation to aquaporins and hydrocephalus." (PMID 20860832, 2010). "Firstly, a large proportion of AQP1 remains in the apical membrane in response to hydrocephalus and therefore must still contribute to CSF production even in the face of hydrocephalus." (PMID 20860832, 2010). "If AQP1 expression was to be significantly down-regulated in hydrocephalus, its therapeutic potential would be limited." (PMID 20860832, 2010). "Understanding the response of AQP1 to changes in CSF pressure and, in particular hydrocephalus, is important for determining a possible therapeutic potential." (PMID 20860832, 2010). "In this chronic model of hydrocephalus, AQP1 protein and mRNA were unchanged compared to controls at 4 weeks and at 9 months after induction of hydrocephalus." (PMID 20860832, 2010). "AQP4 deficiency has been linked to accelerated hydrocephalus progression, while the absence of AQP1 appears protective against ventricular dilation." (PMID 40722587, 2025). "TLR4/NF‐κB/NKCC1 and AQP1 can prevent the prosses of hydrocephalus." (PMID 39450988, 2024). "Moreover, the upregulation of AQP5 and downregulation of AQP1 with an apical localization in choroid plexus epithelial cells were observed in hydrocephalus following IVH." (PMID 39839745, 2024). "Increased expression of CP AQP1 may increase the number of water channels activated by an atrial natriuretic factor or other cGMP-producing factors in late hydrocephalus, hence decreasing CSF generation." (PMID 36204139, 2022). "In communicating hydrocephalus, AQP1 expression is also elevated." (PMID 35715859, 2022). "When lateral ventricle injection of kaolin was used to induce hydrocephalus formation, AQP1 mice in the gene deletion group exhibited a 30% reduction in ventricle dilation, a faster weight recovery following surgery, and significantly fewer side effects such as aberrant behavior." (PMID 36204139, 2022). "There may also be a mechanism for endocytosis of AQP1 in the CPE to slow down CSF secretion during hydrocephalus." (PMID 35715859, 2022). "This AQP1 decrease is described in other types of hydrocephalus." (PMID 36293145, 2022). "Reduced AQP-1 expression can reduce CSF production, which is protective for hydrocephalus." (PMID 35151337, 2022). "AQP1 localisation within choroid plexus epithelial cells was shown to be altered in a kaolin-induced hydrocephalus model of mice, in which there was an increase in intracellular vesicle expression of AQP1 coinciding with a decrease in apical membrane expression." (PMID 30967147, 2019). "However, further studies have indicated a more heterogenous expression of AQP1 in cases of hydrocephalus, but still supporting an adaptive mechanism that decreases AQP1 expression." (PMID 28036023, 2016). "In may be a reflection of an early and temporary reduction in AQP1 transcription in response to hydrocephalus." (PMID 20860832, 2010). "Our finding that choroidal AQP1 is internalised after induction of hydrocephalus secondary to kaolin injection in the mouse also supports this notion and we speculate that this may be a form of compensatory response to hydrocephalus." (PMID 20860832, 2010).
Hydrocephalus (continued). "Thus, selective inhibition or down-regulation of AQP1 expression, combined with enhancement of this protective negative feedback loop, can further reduce CSF secretion and intracranial pressure and delay the pathological process of hydrocephalus." (PMID 36204139, 2022). "Upregulation of AQP has been found in several types of hydrocephalus or other related diseases, for example, upregulation of AQP1 and AQP4 in SAH, suggesting that we may be able to inhibit CSF secretion and alleviate hydrocephalus by downregulating AQP symptoms." (PMID 35715859, 2022). "Further study with the simultaneous evaluation of AQP1 and AQP4 expression will be helpful to confirm the role of AQP4 in the development of hydrocephalus after IVH." (PMID 37208490, 2024). "This study was designed to investigate AQP1 expression in specific brain regions corresponding to the severity of hydrocephalus, while detecting whether regulating the NF‐κb mediated pNKCC1‐pSPAK complex in choroid plexus epithelia can ease the process of hydrocephalus." (PMID 39450988, 2024). "The increase in AQP1 and AQP4 expression during hydrocephalus can be a compensatory mechanism to increase fluid clearance in the brain." (PMID 39364470, 2024). "And attenuated abnormal CPE secretion and hydrocephalus by inhibiting TLR4 / NF-κB / NKCC1 and AQP1." (PMID 39839745, 2024). "In obstructive hydrocephalus and subarachnoid hemorrhage (SAH), the expression of both AQP1 and AQP4 rises, probably to speed up water transport, allowing an increase in the water content of the CSF, thus decreasing the osmotic pressure." (PMID 35715859, 2022). "The present study focuses on the expression of AQP1 and AQP4 in the brain tissue and CSF of SHR and WKY rats to determine the time course of the development of spontaneous hydrocephalus and brain water balance along with chronic HT." (PMID 36293145, 2022). "This work analyzes the expression of the four most abundant aquaporins (AQPs) (AQP1, AQP4, AQP9, and AQP11) in the brains of mice and discuss their contribution to hydrocephalus." (PMID 35454119, 2022). "Viewed together, our AQP1 and AQP4 data correlates with a reduced magnitude of hydrocephalus after USSC treatment consistent with improved CSF fluid homeostasis." (PMID 33897371, 2021). "AQP1 inhibitors can be used for the therapy of human hydrocephalus and disorders of increased ICP from the important clinical enlightenment of the reduced ICP and CSF production in AQP1-KO mice." (PMID 31023968, 2019). "Compared to normal control tissue, the choroid plexus in hydrocephalus cases exhibited more pronounced basolateral AQP4 immunoreactivity and increased AQP1 immunoreactivity in the cytoplasm and at the apical plasma membrane." (PMID 28184993, 2017). "Therefore, specific AQP1 inhibition or down-regulation and strengthening of this beneficial negative feedback can further limit CSF secretion, reduce intracranial pressure, and postpone the pathological progression of hydrocephalus, which may also be a promising therapeutic target." (PMID 36204139, 2022). "Brain aquaporin 1 (AQP1) and AQP4 are involved in cerebrospinal fluid (CSF) homeostasis and might participate in the origin of hydrocephalus." (PMID 34597351, 2021). "There was a statistically significant increase in AQP1 as a result of hydrocephalus (1.86 ± 0.29 relative to WT), and this was not reversed by antagonist treatment (1.95 ± 0.44)." (PMID 32938829, 2020). "Thus, even if no clinical case of hydrocephalus has been related to a pure deficiency of aquaporins, we performed a molecular analysis of Colton antigen expression during blood tests (Colton antigen is found on AQP1), in order to investigate any mutation of AQP1." (PMID 25165051, 2014). "Secondly, we found that AQP1-null mice do not develop hydrocephalus, or at least, the degree of ventricular dilation achieved in the cisternal kaolin-injection model, is much less than that in wild-type mice." (PMID 20860832, 2010).
Hydrocephalus (continued). "This raises the possibility of treatments that upregulate or restore AQP1 expression in aged humans, whose CFS turnover is damaged by Alzheimer’s disease or normal pressure hydrocephalus, by applying an opposite therapy to the one used to manage hydrocephalus." (PMID 21119881, 2010). "Determining the importance of AQP1 and 4 in hydrocephalus and CSF production would be facilitated by the availability of a non-toxic specific AQP1 or 4 blocking agents." (PMID 20860832, 2010). "While AQP1 does appear to contribute to CSF production, its role in the pathophysiology of hydrocephalus has not been well studied and remains unclear." (PMID 20860832, 2010). "Experiments have demonstrated that AQP1-null mice exhibit a fivefold reduction in osmotic water permeability in the choroid plexus compared to wild-type mice, indicating that reducing the function of AQP1 decreases the occurrence of non-obstructive hydrocephalus." (PMID 39944892, 2025).